PCK1 (phosphoenolpyruvate carboxykinase 1)
Diseases named in the same sentence as PCK1 in open-access papers (continued):
Sharing a sentence is not in itself a finding about the gene and the disease.
tumor (continued). "In summary, the clinical validation supported the findings that PCK1 suppresses KAT5 O-GlcNAcylation and inhibits tumor metastasis in human primary HCC." (PMID 34650217, 2021). "Among the ones known to have tumor suppressive functions, we have focused on carboxypeptidase C (CPE), phosphoenolpyruvate carboxykinase 1 (PCK1), and phospholipase C-like 1 (PLCL1)." (PMID 32762776, 2020). "For example, glycolysis-associated enzymes such as phosphoenolpyruvate carboxykinase 1, 2 (PCK1, 2) and enzyme fructose-1,6-bisphosphatase 1 (FBP1), were downregulated in in two tumors, which resulted in glucose intake and kept tumor cells survive." (PMID 32127786, 2020). "The present study revealed that the gluconeogenic enzyme PCK1 negatively regulates cell cycle progression and cellular proliferation via the AMPK/p27Kip1 axis, indicating a tumor suppressor role for PCK1 in HCC." (PMID 30717766, 2019). "In particular, it should be noted that in view of the inconsistent effects of PCK1 in gluconeogenic and non-gluconeogenic tumors, different therapeutic strategies should be considered in future targeted tumor therapy for different tumor types." (PMID 39578429, 2024). "Subclusters 2 and 8 exhibited high expression of the metabolic factors CYP3A4, OTC, PCK1 and TAT, suggesting that these genes may be involved in tumor cell metabolic reprogramming events." (PMID 38927691, 2024). "PCK1 has antitumorigenic effects in gluconeogenic organ cancers (liver and kidney) but tumor-promoting effects in non-gluconeogenic organ malignancies." (PMID 38791477, 2024). "Studies on the nonclassical and nonenzymatic functions of PCK1 have improved our understanding of tumor metabolic enzymes." (PMID 39578429, 2024). "In tumor cells activated by tyrosine kinase receptor or the KRAS oncogene, AKT(Protein Kinase B, PKB) phosphorylates serine at 90 of PCK1, and phosphorylated PCK1 translocates to the endoplasmic reticulum and loses its original gluconeogenic metabolic enzyme function." (PMID 39578429, 2024). "PCK1 phosphorylates INSIG1/2 using GTP as a phosphate donor to block its binding to intracellular lipids, thereby promoting the activation of the SREBP signaling pathway and lipid synthesis in tumor cells." (PMID 39578429, 2024). "We tested PCK1 protein expression in 491 pairs of paraffin-embedded CRC and normal epithelium tissues by IHC and found that almost 90% of CRC expressed lower PCK1 levels than those in non-tumor tissues." (PMID 37062825, 2023). "PCK1 with protein kinase activity can phosphorylate INSIG1/2, which leads to impaired binding of INSIG1/2 with intracellular lipids, thus promoting the activation of the SREBP signaling pathway and lipid synthesis of tumor cells." (PMID 36387147, 2022). "Given that the anti-tumor effects of NFYAv2 are achieved through gluconeogenesis and that NFYA regulates gluconeogenic enzyme PCK1 expression in hepatocytes, we next examined the expression of PCK1 to determine how the NFYAv2 regulates gluconeogenesis in HCC." (PMID 36092708, 2022). "For this purpose, tumor-specific CD4 and CD8 T cells were shown to increase their effector functions to slow tumor growth by increasing PEP production through the over-expression of phosphoenolpyruvate carboxykinase 1 (PCK1)." (PMID 34638609, 2021). "Finally, we assessed PCK1, c-Myc, Twist1, E-cadherin expression and KAT5 O-GlcNAcylation in 48 paired human HCC tissues and tumor-adjacent tissues." (PMID 34650217, 2021). "Further validation via another database revealed that 4 hub genes, ACAT1, SLC2A2, PCK1 and ABAT, were correlated with tumor survival of HCC in T2DM with HbA1c ≥ 6.5%, suggesting the prognostic prediction function of these 4 genes and even new therapeutic targets in HCC." (PMID 33865459, 2021). "Inhibition of the responsible enzymes, PCK1 or PCK2, thus might interfere with adaptation and suppress tumor growth." (PMID 33540663, 2021).
tumor (continued). "In addition, tumor‐specific CD4+ and CD8+ T cells increase phosphoenolpyruvate (PEP) production by overexpressing phosphoenolpyruvate carboxykinase 1 (PCK1), thereby inhibiting sarco/ER Ca2+‐ATPase (SERCA) activity." (PMID 34766109, 2020). "Notably, metabolic reprogramming of TILs, by overexpression of phosphoenolpyruvate carboxykinase 1 (PCK1), that converts oxaloacetate (OAA) into PEP, increases their anti-tumor activities in the glucose-deprived TME." (PMID 32528879, 2020). "In contrast, PCK1 depletion did not impact subcutaneous tumor growth in the SW480 or LS174T cell lines." (PMID 31841108, 2019). "In addition, the AMPK activator metformin remarkably suppressed the growth of PCK1-knockout PLC/PRF/5 cells and inhibited tumor growth in an orthotropic HCC mouse model." (PMID 30717766, 2019). "Furthermore, western-blot analysis was used to analyze the expression levels of PCK1 and TXNRD1 in the xenograft tumor tissues." (PMID 30619751, 2018). "To clarify the function of PCK1 during the carcinogenesis of HCC, we first analyzed PCK1 expression levels in an independent cohort of 373 HCC samples (including 50 paired HCC tissues and para-tumor tissues) from The Cancer Genome Atlas (TCGA) database." (PMID 30619751, 2018). "Tumor-specific CD4 and CD8 T cells could be metabolically reprogrammed by increasing PEP production through overexpression of phosphoenolpyruvate carboxykinase 1 (PCK1), which bolstered effector functions." (PMID 27774525, 2016). "Consequently, PCK1 inhibits GTP-dependent cGAS activation and subsequent STING-promoted immune cell infiltration and activation in the tumor microenvironment, thereby promoting tumor growth in mice." (PMID 40567603, 2025). "Consequently, tumor cells with high PCK1 expression can use nonsugar energy, such as lactic acid and glutamine, to meet the needs of cancer cell proliferation in an environment of glucose deficiency." (PMID 39578429, 2024). "In non-gluconeogenesis tissues, such as lung cancer and colorectal cancer, tumor cells with the expression of PCK1 can use non-sugar energy sources to carry out partial gluconeogenesis because of the lack of downstream key enzymes of gluconeogenesis, such as FBP and glucose-6-phosphatase (G6P)." (PMID 37064872, 2023). "This phosphorylation of INSIGs by phosphorylated PCK1 could reduce the binding of sterols to INSIGs and impairs the interplay between INSIGs and SCAP, contributing to the activation of SREBPs and downstream lipogenesis-related genes, and tumor proliferation." (PMID 37250903, 2023). "It was reported that the expression of gluconeogenic enzymes PCK1, PCK2, and FBP1 predominantly decreased in HCC, and their forced expression induced apoptosis under glucose deprivation conditions, demonstrating the anti-tumor effects of gluconeogenesis in HCC." (PMID 36092708, 2022). "In addition, the expression levels of AKT pS473, PCK1 pS90, INSIG1 pS207/INSIG2 pS151, and nuclear SREBP1 are higher in 451 analyzed human NSCLC specimens than in their adjacent normal tissues and positively correlated with each other in the tumor specimens." (PMID 33842305, 2021). "Enforced expression of phosphoenolpyruvate carboxykinase 1 (PCK1), which presumably increases gluconeogenesis from lactate and thus alleviates the stress from glucose restriction in the TME, has been shown to enhance anti-tumor T cell responses in animal models." (PMID 31114756, 2019). "Consequently, this treatment abrogates PCK1‐mediated phosphorylation of Insig1 at S207 and Insig2 at S151, reduces the nuclear accumulation of SREBP1, and decreases SREBP1 activity‐dependent expression of lipid synthesis genes, lipid accumulation, and tumor cell proliferation." (PMID 40959854, 2025). "Consequently, elucidation of the tumor-specific regulation of PCK1 metabolism and nonmetabolism may help better identify therapeutic targets and develop therapeutic strategies." (PMID 39578429, 2024).
tumor (continued). "Furthermore, phosphoenolpyruvate carboxykinase 1 (PCK1), the rate-limiting enzyme in gluconeogenesis, also facilitates lipogenesis by promoting the translocation of the SCAP-SREBP complex to the Golgi apparatus, activating SREBPs and ultimately promoting tumor cell proliferation and tumorigenesis." (PMID 38833109, 2024). "We found that phosphoenolpyruvate carboxykinase 1 (PEPCK1), a pivotal enzyme in gluconeogenesis, is paradoxically upregulated in tumors by HDS, but not by normal dietary sugar (NDS), during tumor progression." (PMID 39261338, 2024). "In subsequent experiments, SK-Hep1 cells, which do not express PCK1 and G6PC under normal conditions, were selected because we wanted to examine the anti-tumor effects of induced gluconeogenesis in HCC." (PMID 36092708, 2022). "Similar to PCK1 inhibition by shRNA, pre-treatment of cells with 3 MPA significantly reduced (p=0.01) mCRC liver colonization in vivo, Pre-treatment of LS174T cells with 3 MPA did not, however, alter subcutaneous tumor growth." (PMID 31841108, 2019). "Moreover, correlation analysis revealed that PCK1 protein abundance was positively correlated with H3K9me3 in HCC tumor samples (r = 0.4092, P = 0.0035), while negative correlations were observed between S100A11 and H3K9me3 (r = –0.4235, P = 0.0024) and PCK1 (r = –0.5169, P = 0.0001)." (PMID 37166978, 2023).
cancer (61 papers, 2015 to 2026). A tumor composed of atypical neoplastic, often pleomorphic cells that invade other tissues. "Compared to the blank group, the high-fat diet-fed model group showed significantly higher AHSG, G6PC, PCK1, and plasma glucose levels, fat accumulation, and cancer risk." (PMID 40869014, 2025). "The results showed that low PCK1 expression was an independent factor predicting worse DFS, and tumors with low PCK1 expression were associated with a 2.23-fold increase in the risk of cancer recurrence or metastasis (hazard ratio = 2.23, 95% confidence interval [1.02–4.89], P = 0.033)." (PMID 37062825, 2023). "By reducing Pck1 levels, Sweroside disrupts tumor metabolism, a mechanism of considerable importance for therapeutic strategies targeting metabolic disorders in cancer." (PMID 40799828, 2025). "This activation resulted in the suppression of phosphoenolpyruvate carboxykinase 1 (Pck1), a metabolism-related enzyme that is frequently overexpressed in various cancers." (PMID 40799828, 2025). "The diversity of PCK1 expression in different cancer models makes it a challenging therapeutic target." (PMID 39578429, 2024). "Compelling evidence suggests that PCK1 is strongly expressed in CRC cells and that PCK1 promotes cancer cell proliferation by increasing the anabolic utilization of glucose and glutamine." (PMID 39578429, 2024). "In general, PCK1 combines gluconeogenic-tricarboxylic acid-glycolysis to play a complex synergistic regulatory role in cancer." (PMID 39578429, 2024). "More surprisingly, PCK1 plays a role in promoting cancer proliferation and metastasis and plays an inhibitory role in the proliferation and metastasis of CRC." (PMID 39578429, 2024). "We also propose a future exploration direction for targeting PCK1 for cancer therapy from a clinical perspective." (PMID 39578429, 2024). "Regulating PCK1 expression and activity in various cancers involves interplay between metabolic and oncogenic pathways." (PMID 39578429, 2024). "Among the transcription factors, SP1 was the only regulator that was common in both LPL and PCK1, and it mainly plays a role in transcriptional mis-regulation in cancer." (PMID 38791477, 2024). "Accordingly, targeting PCK1 to inhibit lipid production is a promising strategy for treating related cancers." (PMID 39578429, 2024). "Simultaneous knockdown of the PCK1 and mTOR pathways can overcome the inhibition of cancer cell proliferation." (PMID 39578429, 2024). "Herein, we provide a comprehensive overview of the functions of PCK1 under physiological and pathological conditions and suggest that PCK1 is a potential target for cancer therapy." (PMID 39578429, 2024). "In the following sections, we will specifically investigate the role and transformation of PCK1 in various cancers." (PMID 39578429, 2024). "Currently, some clinically available drugs that target PCK1 to modulate PCK1-driven metabolic responses are effective against cancer progression." (PMID 39578429, 2024). "We propose that targeting PCK1 can be combined with chemoradiotherapy to increase the sensitivity of cancer cells to chemoradiotherapy by blocking the blood supply of cancer cells." (PMID 39578429, 2024). "Overall, the findings are compatible with the proposal that MLK4 is an upstream regulator of PCK1, and it mediates its metabolic effect on cancer cells through the transcriptional activation of PCK1." (PMID 37407566, 2023). "Our finding shows that gluconeogenesis-related key enzyme PCK1 was downregulated in cancer tissues of HCC than in normal tissues." (PMID 38017546, 2023). "We were aware that PCK1 in cancer metabolism was most relevant in conditions with scarcity of glucose, therefore, we further performed MLK4 knockdown in cells which were cultured in medium significantly deprived of glucose." (PMID 37407566, 2023).
cancer (continued). "Gluconeogenesis is the synthesis of glucose from non-carbohydrate precursors and can antagonize aerobic glycolysis in cancer via the gluconeogenesis-related key enzymes PCK1/PCK2, FBP, and G6PC." (PMID 38017546, 2023). "To reverse the inhibited status of gluconeogenesis in cancer cells, we introduced the key enzyme PCK1 into two cancer cell lines using lentivirus." (PMID 37553601, 2023). "The overexpression of PCK1 led to an increase of cellular glucose levels and a decrease in lactate levels in both cancer cell lines." (PMID 37553601, 2023). "Several cancer cell lines have been described as having high expression of Pck1 that drive proliferation." (PMID 36455788, 2022). "In these cancer types, patients with high expression of PCK1 or G6PC showed a better prognosis than those with low expression." (PMID 36092708, 2022). "Subsequently, PCK2 or PCK1 have been found to be active especially under conditions of glucose deprivation to promote cell survival or proliferation in diverse cancer types." (PMID 33540663, 2021). "In NSCLC, PCK1-induced nuclear SCAP-sterol regulatory element-binding protein 1 (SREBP1) activation is required for cancer progression." (PMID 34620839, 2021). "The downstream metabolic pathways fueled by PCK1 or PCK2 in cancer cells include the biosynthesis of the phospholipid glycerol backbone, serine, or ribose." (PMID 32777161, 2020). "Mechanistic studies revealed that PCK1 enhances pyrimidine nucleotide biosynthesis, which enables cancer cell growth in the context of hypoxia—a key feature of the liver microenvironment." (PMID 31841108, 2019). "The cytoplasmic isoform of phosphoenolpyruvate carboxykinase (PCK1 or PEPCK-C), a rate-limiting enzyme in gluconeogenesis, initiates the gluconeogenesis process and is reportedly dysregulated in multiple types of cancer." (PMID 30619751, 2018). "Significant correlation between mTOR-dependent upregulation of PCK1 and cell death in different cancer cell lines further emphasizes the physiological relevance of this pathway." (PMID 27551450, 2015). "Further experiments confirmed that PCK1 has a cancer-promoting effect." (PMID 39578429, 2024). "Significantly down-regulated genes in cancer tissue, compared to normal tissue included PLA2G2A, MUC4, PCK1, TXNIP, and genes encoding the CCR7 ligands, CCL19 and CCL21, which are lymphoid chemokines involved in the chemotaxis of lymphoid cells such as leukocytes and dendritic cells." (PMID 38505585, 2024). "Finally, in view of the collective data, the results of our discussion suggest the potential clinical application of targeted PCK1 therapy in combination with chemotherapy and immunotherapy for cancer treatment." (PMID 39578429, 2024). "Post-translational modifications (PTMs) of the PCK1 protein, such as acetylation, phosphorylation, sumoylation, and ubiquitination, affecting its protein stability have been continuously found in diseases, including cancer." (PMID 39578429, 2024). "In addition, phosphoenolpyruvate carboxykinase 1 (PCK1) catalyzes the conversion of oxaloacetate (OAA) into PEP, and the overexpression of PCK1 enhances the cancer-killing functions of adoptive transferred CD4+ and CD8+T-cells." (PMID 36768924, 2023). "PCK1 is considered an anti-oncogene in several human cancers." (PMID 37062825, 2023). "Most of these studies proposed the cancer-promoting function of PCK1 in different types of cancer." (PMID 34620839, 2021). "Recent studies have proposed a pivotal function of PCK1 in human cancer tumorigenesis progression." (PMID 34620839, 2021). "The downstream metabolites generated via PCK1 or PCK2 in glucose-deprived cancer cells include all the biosynthetic precursors classically considered to be derived from glucose: the phospholipid glycerol backbone, serine and glycine used for purine biosynthesis and ribose phosphate." (PMID 33540663, 2021).